APP (amyloid beta precursor protein)
Diseases named in the same sentence as APP in open-access papers (continued):
Sharing a sentence is not in itself a finding about the gene and the disease.
cancer (continued). "The human cancer-related blue module is more strongly preserved in the tau transgenic mouse network than the APP mouse network." (PMID 36879821, 2023). "APP, Cyclin D, and Cyclin E are simultaneously up-regulated in cancer and neurodegeneration, and PTPA tended to be down-regulated." (PMID 37383425, 2023). "It is therefore necessary to study the HGprt enzyme, AT, and APP using expression vectors for exploring their impact on LND, thrombosis as well as other human diseases, especially the ones related to APP such as AD and cancer." (PMID 35860682, 2022). "As a perspective, for clarification of these issues, it is necessary to study the HGprt enzyme and APP using expression vectors for exploring their impacts on LND as well as other human diseases, especially the ones related to APP such as AD and cancer." (PMID 35860682, 2022). "Two hub genes, including CAT and APP, are involved in different cancers; for Instance, CAT, positioned specially in peroxisomes, decomposes H2O2, a spinoff of fatty acid oxidation, to oxygen and water." (PMID 36302939, 2022). "Roles for TMED9 in the regulation of cancer cell growth, APP processing, and protein degradation underscore the importance of this cargo receptor in health and disease." (PMID 36733337, 2022). "APP is a cell membrane protein that is closely related to tumor growth and metastasis and functions as a tumor-promoting factor in cancer." (PMID 36561345, 2022). "APP has also been suggested as a molecule involved in cell proliferation and invasion in various human cancers, including non-small-cell lung cancer." (PMID 36302939, 2022). "Carcinoma cells were also stained with antibodies against different isoforms of APP, but most distinctively anti‐APP antibody marked blood vessel walls within the tumor." (PMID 34592066, 2022). "Applying immunocytochemistry, we found that all tumor samples had both APP and Aβ staining in a majority of the carcinoma cells (yellow arrows)." (PMID 34592066, 2022). "We detected significant presence of amyloid precursor protein (APP) in the walls of blood vessels of tumor samples, as well as in carcinoma cells." (PMID 34592066, 2022). "Otherwise, the surface expression of HGprt enzyme was also observed in several somatic tissue cancers while APP and the APP-like protein-2 (APLP2) are deregulated in cancer cells and linked to increased tumor cell proliferation, migration, and invasion." (PMID 34877405, 2021). "Overexpression of APP and TRIM25 in cancer patients was associated with low overall survival and the reverse was true for ELAVL1." (PMID 34193143, 2021). "This network was composed of central functional components associated with metabolism and cancer such as TNF, MAPK, TRIM21 and one component contained APP." (PMID 32228434, 2020). "Our work shows that EPB41L1 and its co-expressed gene APP are coordinated to regulated cancer cell adhesion, which can increase the incidence of cancer cell metastasis and tumor invasion and lead to higher mortality in KIRC patients." (PMID 32760223, 2020). "ppGalNAc-T2, another O-type glycosyltransferase involved in APP processing, also appears to act in both modes with respect to cancer." (PMID 33218200, 2020). "The expression of APP at cancer stages, tumor grades, KIRC subtype, nodal metastasis status, patients’ gender, and age, and in the TCGA database showed that the down-regulation of APP expression nearly existed in all subtypes of KIRC." (PMID 32760223, 2020). "APLP1 is closely related to APP and APLP2, both of which are associated with aggressive cancers in other organs." (PMID 30603059, 2018). "APP and the related amyloid precursor-like protein 2 also have, somewhat surprisingly, significant cancer modulating effects, including increased tumor cell proliferation, migration, and invasion." (PMID 29587359, 2018). "Recently, it has been reported that several types of cancers have increased expression of APP, which correlated with increase cancer cell proliferation." (PMID 26673618, 2016).
cancer (continued). "Altogether, these findings suggest a potential role of APP in cancer and in anticancer drug response." (PMID 25926793, 2015). "ADAM10 is a sheddase that cleaves ectodomains of transmembrane proteins such as E-cadherins, N-cadherins, Notch, CD44 and amyloid precursor protein (APP), which play a significant role in proliferation, migration, invasion or stemness of cancer cells." (PMID 26440150, 2015). "The inhibition of membrane targeting interferes with the cellular functions of APP and Notch, which includes signaling associated with enhanced growth, EMT, migration, invasion and stemness of cancer cells." (PMID 26440150, 2015). "This idea is supported by recent studies reporting up-regulation of APP in several cancers due to its growth-promoting function." (PMID 25056661, 2014). "Upon stimulation with IGF-1 that promotes cell migration and cancer metastasis, APP-kd cells migrate slowly in response to IGF-1 partly due to limited activation of AKT." (PMID 25491510, 2014). "APP has been found to be up-regulated in many cancers, including pancreatic, colon, and prostate cancer and squamous cell carcinoma." (PMID 25056661, 2014). "Recently, the increased expression of APP in multiple types of cancers has been reported where it has significant correlation with the cancer cell proliferation." (PMID 25491510, 2014). "The potential role of APP in cancer cell motility is also supported by studies which show APP plays a role in migration of neuronal precursor cells and neurite outgrowth." (PMID 25491510, 2014). "On the other hand, APP is also over-expressed in cancer of oral cavity, esophageal, pancreatic, neuroendocrine, thyroid, and colorectal cancers." (PMID 24858274, 2014). "Another miRNA family, the let-7 family, in addition to its involvement in the regulation of APP in AD in C. elegans, seems to have a role in many types of cancer through its regulatory effects on a variety of target proteins such as Ras, HMGA2 and Myc." (PMID 24858274, 2014). "Given that APP is a known cell adhesion protein and ferroxidase, this suggests biochemical links among cell signaling, the cell cycle, iron metabolism in cancer, and AD in the context of overall aging." (PMID 23368879, 2013). "Involvement of APP expression is also suggested in cancer cells originating from the nasopharynx, oral cavity, thyroid, and colon." (PMID 23662100, 2013). "Among these, LAMA2, DUSP1, PRKAR1B, and APP were downregulated while the rest of the genes were upregulated in cancer as compared to normal cervical samples in the samples used for microarray." (PMID 24403257, 2013). "In the same study, small interfering RNA-mediated knockdown of APP also resulted in decreased cancer cell growth." (PMID 23662100, 2013). "The reason for this is unclear but a recent study demonstrated that APP plays a role in growth of cancer cells." (PMID 21527012, 2011). "The specific cancer cell lines were injected subcutaneously and tumor growth rates and final tumor volumes were compared between the A53T α-Syn+/+ mice, modeling PD; APP/PS1, modeling AD; and control genotypes including, F1 B6/C3H, B6 and C3H." (PMID 21611169, 2011). "APP is also shown to be involved in proliferation and migration of cancer cells." (PMID 41226668, 2025). "APP possesses a wide range of cellular functions, such as the regulation of cellular adhesion, differentiation, and migration, which are also essential processes for cancer development." (PMID 39090420, 2025). "The aim of this systematic review is to summarize the current scientific evidence on the effects of androgens on APP processing in cancers, with the hope of identifying new potential therapeutic targets and highlighting critical knowledge gaps where further research is needed." (PMID 41614805, 2025). "While APP overexpression and androgen receptor (AR) signaling are each associated with cancer progression, the connection between androgens and APP processing in cancer has not been thoroughly investigated." (PMID 41614805, 2025).
cancer (continued). "It will also be important to explore the effects of androgen receptor inhibitors used in cancer therapy on APP pathways, and to determine whether the products of these pathways, including sAPPα or sAPPβ, contribute to disease development." (PMID 41614805, 2025). "Understanding APP's influence on cancer cell behaviour and interaction with the TME could revolutionize ccRCC treatment strategies." (PMID 38445803, 2024). "Pathway analysis of overlapping up- and downregulated genes in PSEN and APPV717I neurons showed some common significantly dysregulated pathways including cancer-related pathways and cellular senescence, suggesting convergent dysregulated pathways affected by familial PSEN and APP mutations." (PMID 38918213, 2024). "Further analyses indicated that FASN and APP were promising targets for anti-cancer therapy." (PMID 39332525, 2024). "Interestingly, the coordinated regulation of cancer cell adhesion by APP and EPB41L1 points to the possibility of these proteins as key factors in the progression of ccRCC." (PMID 38445803, 2024). "Moreover, APP and APP-like protein-2 (APLP2) are deregulated in cancer cells and linked to increased tumor cell proliferation, migration, and invasion." (PMID 36980958, 2023). "The role of APP and its processing secretases has been widely studied in neurodegenerative diseases; however, few studies have also demonstrated their role in the development and progression of various cancers." (PMID 38201438, 2023). "APP plays a role in cancer progression and metastasis formation, and APP inhibits proteinases." (PMID 36979388, 2023). "In addition, APP has been found to be overexpressed in various cancers, including breast cancer and can promote cancer cell migration and invasion." (PMID 35882892, 2022). "Moreover, lymph cells highly express other signaling pathways that can be ultimately connected to interactions between cancer cells and T cells, such as APP, CD99, MHC-I, and CD46." (PMID 34830900, 2021). "Recently, increasing evidence suggests an important function of APP as a potent tumor growth factor in the pathogenesis of several somatic tissue cancers, and APP as well as APLP2 are deregulated in cancer cells and linked to increased tumor cell proliferation, migration, and invasion." (PMID 34877405, 2021). "In some cancers, APP and APLP regulate proliferation, migration, and disease progression." (PMID 34066808, 2021). "APP relates to cancer cell viability, proliferation, migration and invasion." (PMID 34249502, 2021). "Thus, APP is involved in the proliferation of cancer cells as well as in their adherence and movement and its exaggerated synthesis is considered a potential prognostic factor in ER-positive breast cancer patients." (PMID 32391121, 2020). "The cooperative regulation of EPB41L1 and APP in cancer cells may indicate a special adhesion mechanism that can synchronize increased cell adhesion based on regulating cell adhesion-related pathway." (PMID 32760223, 2020). "In cancer cells, APP was demonstrated to regulate ADAM17 gene expression." (PMID 29988083, 2020). "Among cancers with low MHC class I antigen processing pathway (MHC-I APP), histone modifications were seen in MHC-I APP gene promotors, leading to transcriptional silencing and decreased expression of MHC class I, causing loss of antigen presentation and immune evasion." (PMID 35582437, 2020). "Moreover, the binding of DR6 to its ligand APP (amyloid precursor protein) promoted endothelial cell death and cancer cell extravasation." (PMID 31122251, 2019). "For example, the amyloid precursor protein (APP) community involved in 58 pathways (i.e., highest degree) across 15 cancers was found to be implicated in common cancer features, such as the induction of necroptotic endothelial cell death to promote metastasis and tumor cell proliferation." (PMID 31311925, 2019).
cancer (continued). "Others, pertinent to the DS, Alzheimer’s, and cancer relationship, include the APP gene, transcriptional factors such as ETS proto-oncogene 2 (ETS2), the angiogenesis suppressors Dscr1 and Dyrk1A and the collagen-18 gene whose fragment, endostatin, is an anti-angiogenic compound." (PMID 29587359, 2018). "Pathway analysis of significantly mutated and cancer driver genes involved MAPK/ERK and Amyloid Beta Precursor Protein (APP) pathways, whereas analysis of copy n umber alterations and gene expression data indicated a deregulation of the MAPK/ERK and NF-kB pathways." (PMID 30060526, 2018). "The cancer-stimulating activity of APP could act in synergy with similar activities of leptin, and the neuroprotective APP alpha secretase product could synergize with the neuroprotective activity of leptin." (PMID 29587359, 2018). "This situation could present a clinical conundrum in how to treat patients with cancers overexpressing APP and thus warrants further investigation." (PMID 25926793, 2015). "In addition, APP expression is indirectly linked to Ras/MAPK and PI3K/Akt pathways, which are often upregulated in various cancers (Ruiz-León and Pascual, 2004)." (PMID 25926793, 2015). "Since the characteristics of 3D morphology may represent functional and genetic alteration of cancer cells as shown in altered E-cadherin expression, the 3D morphological change of APP-kd cells would result in behavioral and functional conversion." (PMID 25491510, 2014). "The mechanism of APP expression in cancer cells is not fully understood." (PMID 23662100, 2013). "These functions are important in carcinogenesis, and APP expression may be involved in the development of various cancers." (PMID 23662100, 2013). "These lines of evidence suggest that APP is involved in cancer cell proliferation." (PMID 23662100, 2013). "The results indicate that activating LXR with the ligand GW3965 or the FDA-approved antiskin cancer drug bexarotene reduces soluble and insoluble Aβ and improves cognition in APP Tg mice, while knocking out the ABCA1 gene in APP mice showed a tendency to reduced amyloid load." (PMID 22844635, 2012). "As our review highlights, since the early reports on APP in relation to androgens, there has been follow-up, but it is limited, and hopefully, with better collaborative approaches between researchers in AD and cancer, this is one pathway that warrants further investigation in the cancer space." (PMID 41614805, 2025). "Investigating whether androgen-induced ADAM10 upregulation shifts APP processing toward sAPPα production and how this affects cancer biology will be critical for determining whether targeting and enhancing ADAM10 could serve as a therapeutic strategy for cancer." (PMID 41614805, 2025). "Additionally, the study explored the role of APP in cancer progression." (PMID 41614805, 2025). "APP is also reported as one of the diagnostic biomarkers for OS, and its high expression reduces the survival of OS patients but not pan-cancer patients." (PMID 36943734, 2023). "In addition, APP is found to be overexpressed in multiple cancers, such as breast cancer." (PMID 35882892, 2022). "Therefore, the identification of the interaction between Vav2 and APP may open up a novel avenue for further research on the role of APP in cancer." (PMID 35882892, 2022). "Thus, the APP that we observed in tumor blood vessels may be of murine origin, while the carcinoma cells that were injected to form xenografts were of human origin." (PMID 34592066, 2022). "Furthermore, given that APP was the only gene whose expression level was significantly associated with the disease‐free survival of HNSCC patients, this gene may be involved in cancer progression." (PMID 31304688, 2019).
cancer (continued). "Furthermore, the synergistic enhancement in cancer cell killing effect by oAd-vp53/APP complex was cancer-specific, since oAd-vp53/APP complex induced minimal level of cytotoxicity that was similar to PTX, oAd-vp53 + PTX, or APP treatment in several normal cell lines." (PMID 32903299, 2019). "APP was hypothesized to be a promoting factor for a variety of malignant tumors." (PMID 31304688, 2019). "There were also significant interactions between insulin-expressing cancer cells and immune cells, namely CD40LG (INS+FOSlow, INS+) − CD40 (B cell) and APP (INS+) − TREM2 + TYROBP (macrophage)." (PMID 40438247, 2025). "According to studies, APP interacts with a variety of signaling pathways, including the mitogen-activated protein kinase (MAPK) pathway, which contributes to cancer progression." (PMID 39123408, 2024). "Secretases can effectively regulate the activation of Notch and amyloid precursor protein (APP), key factors in the progression of AD and cancer." (PMID 39634655, 2024). "Some of the prominent genes we identified through the networks are DOK5, APP, CTNND1, STX6, STX10, STX16, BACE1, and BACE2; which, agree with the regulation of various cancers based on their co-expression patterns in GeneMANIA." (PMID 37218885, 2023). "The targets in the cancer pathways (SRC, EGFR, ESR1, PTGS2, and APP) were used for molecular docking analysis with all active compounds." (PMID 36561345, 2022). "The results exhibited that the mRNA and protein expression levels of PLAU, APP, AREG and CAV2 were upregulated in cancer cells compared to normal cells." (PMID 36437265, 2022). "C3, APP, GAL, and C3AR1 have also been shown to be involved in the regulation of cancer cell metastasis and tumor invasion in multiple cancers." (PMID 34239596, 2021). "In cancer, APP and APLP cleavage involve hormone insulin-like growth factor 1 (IGF-1), which is a well-known regulator of cell growth and cancer progression." (PMID 34066808, 2021). "Further analysis suggested that EPB41L1 and amyloid beta precursor protein (APP) were coordinated to regulated cancer cell adhesion, thereby increasing the incidence of cancer cell metastasis and tumor invasion." (PMID 32760223, 2020). "Among the proteins differentially present in cancer vs. control were six common to both local and metastatic PDAC: Up—GDF15, TIMP1, and IL1RL1; Down—CCL22, APP, and CLEC1B." (PMID 33334063, 2020). "Similar to other cationic nanomaterials, complexation of Ad with APP greatly improved transduction into both CAR-negative and -positive cancer cells." (PMID 32903299, 2019). "It is known that amyloid precursor protein (APP) and its family members amyloid precursor-like protein 2 (APLP2) expression is aberrantly altered in many types of cancers, e.g., pancreatic, colon, breast, prostate, lung, and others." (PMID 31509551, 2019). "For example, Icariside II (ICS II), an anti-cancer natural compound extracted from Herba Epimedii Maxim, was demonstrated to inhibit Aβ production by reducing APP and BACE1 expression in APP/PS1 transgenic mice." (PMID 29358920, 2017). "Over 90 substrates have been identified so far including amyloid precursor protein (APP), Notch and Eph receptors and ligands, cadherins, and deleted in colorectal cancer (DCC)." (PMID 27196744, 2016). "ADAM10 is reported as a sheddase that can cleave transmembrane proteins such as amyloid precursor protein (APP), E-cadherin, N-cadherin, CD44 and Notch, all of which play a significant role in proliferation, migration, invasion or stemness of cancer cells." (PMID 27259866, 2016). "Network 14 and 15 show networks with AKT, and APP, BCL2L1, IGM as a central node, which show cancer, haematological disease, and immunological disease, respectively." (PMID 27463006, 2016).